FOXP3 (forkhead box P3)
Diseases named in the same sentence as FOXP3 in open-access papers (continued):
Sharing a sentence is not in itself a finding about the gene and the disease.
tumor (continued). "We aimed to study 20-year OS in OPSCC patients, with and without disease-specific-death (DSD) patients subtracted and stratified by tumor HPV presence, dependent on the activation level of TILs measured by Foxp3-positive cell numbers." (PMID 36289746, 2022). "In another study utilizing 130 paired samples of CRC tumor tissue and adjacent healthy colonic mucosa samples, significantly higher TSDR-DMRs and increased FOXP3 mRNA and protein expression were also observed in TI-Treg cells." (PMID 35874729, 2022). "Differences in staining of FOXP3 in Tregs and CD8 in tumor-infiltrating lymphocytes in tumor stroma in the Tis group were observed compared with the Tadv group (each P<0.01)." (PMID 35358193, 2022). "Foxp3-GFP/DTR mice were engrafted with MC38-B7x or MC38-Control tumors and subsequently treated with human diptheria toxin (DT), which eliminated tumor-infiltrating Tregs within 2 days." (PMID 35523809, 2022). "The data suggest that high FOXP3 and HER2/neu expression and a high proliferation index are, together, a biomarker of tumor aggressiveness." (PMID 36235242, 2022). "Treg development, maintenance, accumulation, and immnosupression function in VAT and tumor tissues depend upon the expression of TCR, Foxp3, and IL-33." (PMID 35371055, 2022). "This approach not only improved the pharmacokinetic stability and tumor penetrance of both drugs, but co-delivery produced a synergistic improvement in the TME CD8+/Foxp3+ ratio, DC intercalation, and tumor control in a KPC mouse model." (PMID 35154473, 2022). "Tissue microarrays were evaluated for tumor-infiltrating lymphocytes (TILs) assessed morphologically on hematoxylin and eosin-stained slides, and by immunohistochemistry for CD8, FOXP3, LAG-3, PD-1 and PD-L1." (PMID 35954471, 2022). "In the Hdac5 knockdown group, anti-PD-1 treatment dramatically increased the tumor infiltration of CD45+CD8+ and CD45+CD4+ T cells as well as decreased the levels of CD11b+Gr1+ myeloid cells and CD4+Foxp3+ Treg cells in tumors." (PMID 35265200, 2022). "PD-L1 TPS, indicating tumor-specific, and PD-L1 CPS, indicating immune cell and tumor-specific staining, both strongly correlated with STAT1 expression and with cytotoxic CD8- and FOXP3-positive cells." (PMID 35267462, 2022). "Naturally occurring, thymic, Forkhead box protein P3 (FoxP3)+, CD4+ regulatory T cells (Tregs), are sensitive to activation by self-antigens and tumor neoantigens, and are main players of the neoplastic microenvironment." (PMID 35296093, 2022). "Correlations between frequencies of FoxP3+Helios+ Tregs and CD4+TIM-3+ T cells in TME were stronger in advanced tumor stages, compared to early stages (r = 0.793, p = 0.011 [early]; r = 0.771, p = 0.002 [advanced])." (PMID 36146549, 2022). "We found that rAd-mIL-28B significantly inhibited tumor growth and reduced the frequency of splenic CD4+Foxp3+ T cells." (PMID 35935577, 2022). "(B) Frequencies of CD4+ T cells, CD4+Foxp3+ Tregs, and CD8+ T cells within draining lymph nodes (dLN) and tumor of Asm-KO and Asm-WT mice were determined by flow cytometry." (PMID 36426850, 2022). "We also established that TGFβ-induced FOXP3 enhances CCR4 transcription in Treg cells, making them amenable for tumor site infiltration." (PMID 35222362, 2022). "Those lesions exhibited significantly higher densities of tumour microenvironment cellular infiltrate including CD4, FOXP3, CD163 and PDL-1, potentially indicating a role for the inflammatory immune response in disease progression." (PMID 36224403, 2022). "Furthermore, when comparing HCC tissue samples by median of nuclear STAT3 expression, CD3-, CD4-, CD8-, and FOXP3-positive immune cell counts were significantly higher in tumor tissues with high nuclear STAT3 expression compared to tumor tissues with low nuclear STAT3 expression of the tumor cells." (PMID 35267462, 2022).
tumor (continued). "T-VEC is a genetically modified live HSV-1 which decreases the infiltration of CD4+FoxP3+ Tregs and CD8+FoxP3+ suppressor T cells into the tumor microenvironment." (PMID 35865534, 2022). "We found that FoxP3 expression and ICs including PD-1, CTLA-4, TIM-3, and LAG-3 were significantly increased in tumor-infiltrating CD8+ T cells compared with NT and peripheral blood." (PMID 35804964, 2022). "Compared to normal weight (norm) controls, these DIO Tregs displayed increased levels of FOXP3, and PD-1 and KI67 (respectively), markers known to be upregulated on activated, effector-like “eTregs” that accumulate in the tumor niche." (PMID 36289552, 2022). "In the tumor microenvironment, the ratio of CD8+ T cells to CD4 + FOXP3+ regulatory T cells was significantly elevated and exhausted CD8+ T cells (PD-1+, CTLA-4+, TIM-3+, or LAG-3+ cells) were significantly reduced in the triple combination group." (PMID 35681672, 2022). "Cancer progression gene array and immunohistochemical analyses of FOXP3 as a Treg marker, CD8 as a tumor-infiltrating lymphocyte marker, and CXCR4 expression on activated Tregs were conducted in a series of 31 conjunctival SCC cases." (PMID 35358193, 2022). "Compared to Pirc tumor AIN and Pirc tumor SPI3d groups, Pirc tumor SPI samples had reduced Foxp3, Iκbα, and Survivin expression." (PMID 35159382, 2022). "This review focuses on the signaling pathways of FOXP3 in different tumor metastasis processes and clarifies the interaction between anti-tumor TCM and FOXP3, as well as its potential therapeutic effects." (PMID 36235242, 2022). "Overexpression of FOXP3, on the other hand, increased CCR4+ Treg infiltration, resulting in a decreased anti-tumor immune response and tumor progression." (PMID 35222362, 2022). "The treatment with Lip-Dox and Lip-Pep promoted tumor infiltration with TILs and NK cells, stimulated IFN-γ secretion and reduced MDSCs and CD25+Foxp3+ Tregs populations in the TME more efficiently than E75 and Dox alone." (PMID 35335881, 2022). "Biopsies revealed increasing numbers of tumor-infiltrating CD4+/CD8+ lymphocytes and persistent low numbers of Foxp3+ cells." (PMID 35864254, 2022). "First, we flow-sorted GFP+ tumor-infiltrating Tregs from MC38-B7x and MC38-Control tumors engrafted in Foxp3-GFP/DTR mice and performed RNA-seq on the sorted Tregs." (PMID 35523809, 2022). "This study also suggested that FOXP3 can upregulate the expression of MMP2 and MMP9, both of which play a promoting role in tumor metastasis." (PMID 36235242, 2022). "When the CD8+, FOXP3+, and PD‐1+ TAIC densities of all individual tiles were plotted, large intratumoral heterogeneity was observed in the tumor epithelium, tumor stroma, and non‐tumor stroma compartments." (PMID 34743329, 2022). "In mouse models of melanoma and colon cancer, anti-PD-1 treatment induced the expansion of tumor Tregs with a follicular phenotype (Follicular regulatory T cells or Tfr, Foxp3+ Bcl6+), and Tfr depletion by pretreatment with anti-CTLA4 improved tumor control." (PMID 35874810, 2022). "Factor fork head box protein P3 (FOXP3) is always a marker of CD4 + regulatory T cells, which suppress local immunity, aid in tumor cell immune escape and promote tumor development and progression." (PMID 35654816, 2022). "FOXP3 FL and FOXP3-Δ3 have been shown to be expressed in HCC tissues, cell lines, and the mice tumor model." (PMID 36235242, 2022). "Tumor-infiltrating pDCs are also able to recruit other suppressive cells in the tumor microenvironment such as myeloid suppressive cells, IL10+CCR7+CD8+Foxp3+ induced Tregs, and IL-10+ IL-17+ Foxp3neg type-1 regulatory T cells (Tr1)." (PMID 35884612, 2022). "Treatment with OximUNO reduced the progression of primary tumor lesions and pulmonary metastases, significantly diminished the number of CD206+ TAMs and increased the CD8/FOXP3 expression ratio (indicating immunomodulation)." (PMID 36923553, 2022).
tumor (continued). "To further detect the infiltration of T cells in tumor tissue, we examined the number of Granzyme B+CD8+ T cells and FOXP3+ Tregs within the tumor tissues." (PMID 36163134, 2022). "Multiplex-immunofluorescence was performed to determine the presence of cytotoxic T-cells (T-cyt; CD3+CD8+), regulatory T-cells (T-reg; CD3+FOXP3+), T-helper cells (T-helper; CD3+CD8-FOXP3-), B cells (CD20+), dendritic cells (CD11c+) and tumor cells (panCK+)." (PMID 36238289, 2022). "Accumulating evidence indicates that tumor immune microenvironment (particularly regarding PD-1, PD-L1/2, forkhead box P3 (Foxp3), CD80, and CD86 expression) and immune checkpoint signaling play decisive roles in tumor immune evasion and growth." (PMID 36483592, 2022). "If including only DSS patients, predictions were still observed regarding CD3 TIL cells (p = 0.028), FoxP3 TIL cells (p = 0.017) and CD68 tumor cells (p = 0.005)." (PMID 36289746, 2022). "Abundant studies have suggested that Foxp3 regulates the expression of several genes (CTLA-4, PD-1, LAG-3, TIM-3, TIGIT, TNFR2) involved in carcinogenesis to utilize its tumor suppressor function through knockout models." (PMID 36009853, 2022). "To explore the immune cell infiltration in LUSC, we further validate the expression of PD-L1 and FOXP3 between benign nodule and LUSC and found that compared with benign nodule, PD-L1 was significantly up-regulated and FOXP3 was down-regulated in LUSC." (PMID 36465363, 2022). "In their research, the proportions of IL-17+ T cells, CD8+ T cells, Foxp3+ Tregs, Tbet+ T cells, and CD20+ B cells in the central and invasive margins of postoperative tumor tissue from 82 patients (42 of whom received NACT) were analyzed." (PMID 36439457, 2022). "Significantly higher percentages of tumor-infiltrating CD103+ T cells were CD8+ (mean 62.0%) than CD4+ (mean 34.8%, p<0.0001), CD4+FOXP3+ (mean 1.4%, p<0.0001) and CD4+FOXP3− (33.0%, p=0.0009)." (PMID 33479027, 2021). "The FoxP3 count ranged from 0–145.5 per HPF (median: 1.7 per HPF) in the tumor region and 0–6.8 per HPF (median: 0 per HPF) in the non-tumor region." (PMID 34257613, 2021). "A total of 32 samples were selected for CD20, CD68, CD4, Foxp3, CD8, and P16 (for tumor cell staining) expression analysis by multiple immunofluorescence (mIF) staining and CD3 expression analysis by IHC staining." (PMID 35145511, 2021). "We see that the FoxP3+ (and to a lesser extent CD8+) cells support voids at larger radius than CD68+ cells in this tumor." (PMID 34625491, 2021). "We used IHC staining to evaluate the infiltration of tumor-infiltrating inflammatory/immune cells in the CCA microenvironment, including CD8+ T cells, FOXp3+ T cells (Tregs), and CD163+ M2 macrophages (TAMs)." (PMID 34083572, 2021). "PD-L1、B7-H4、FOXP3 and CD163 protein expression in tumor tissues were detected by immunohistochemistry." (PMID 34307135, 2021). "Tumor-bearing mice on daily CR and cycles of FMD and LCC had a significant reduction in the frequency of FoxP3+CD4+ cells in peripheral blood vs. AL-fed controls." (PMID 34707136, 2021). "This study showed that Foxp3 is physically associated with Rcor1, Rcor2, and Lsd1 and that depletion of Rcor1 in Foxp3+ cells leads to enhanced expression of IL-2 and IFN-γ, which provides increased anti-tumor CTL responses." (PMID 34943965, 2021). "Several marker genes, FOXP3, STAT3, PDCD1, TGFB1, IL10, HMGB1, which are significantly related to the tumor microenvironment induced by radiation, had significant functional differences in the distribution of CD8+T cells clusters." (PMID 33968889, 2021). "In some tumors, Foxp3 is related to the activation of CD4 + CD25 + Treg cells, and also affects the development and function of Treg cells, thereby affecting tumor proliferation." (PMID 33784955, 2021).
tumor (continued). "In the local tumor draining lymph node (TDLN), at day 3-4 post cryoablation, increased frequencies of CD8+ central memory T-cells and Foxp3+ CD4+ regulatory T-cells (Tregs) were observed only in the fast freeze group as compared to non-treated controls." (PMID 34149738, 2021). "Pre-clinical study on HNSCC mouse models have shown that SCH58261,a A2AR antagonist, significantly decreases the population of CD4+ FOXP3+ Tregs and promotes a CD8+ T cell-mediated antitumor response, which lead to a delay in tumor growth." (PMID 33422072, 2021). "We also assessed the co-expression of PD-L1 and markers that define specific immune cell subpopulations: CD4 and CD8 for lymphocytes, FoxP3 for regulatory cells, and CD68 for macrophages, as well as PD-L1 expression in cytokeratin-positive tumor cells." (PMID 34572882, 2021). "CD4+ T helper 1 (Th1) cells play a role in protecting against tumor growth, whereas CD4+ Th2 and CD4+ FOXP3+ Treg cells promote tumor growth." (PMID 34680248, 2021). "Significantly more IFN-γ-expressing CD8+T lymphocytes, elevated levels of IFN-γ and IL-2, fewer CD25+ forkhead box P3 (Foxp3) +Tregs and decreased levels of IL-10 and TGF-β were detected at tumor sites." (PMID 33435564, 2021). "The numbers of Foxp3+ cells surrounding the tumor were analyzed by IHC to divide the PDAC tissues into high and low Foxp3+ groups." (PMID 34075561, 2021). "Staining for CD3 together with Foxp3 indicate that CD3+ cells maintained the distribution pattern and morphological characteristics of the native tissue and showed an invasion into the tumor site after nivolumab treatment." (PMID 34564709, 2021). "CD4+ Th1 cells have been shown to prevent tumor growth, while CD4+ Th2 and CD4+ forkhead box P3+ lymphocytes (Tregs) are considered to promote tumor growth." (PMID 34228637, 2021). "A frank tumor-promoting activity is exerted by Tregs, CD4+ T lymphocytes expressing CD25 (the α subunit of IL-2 receptor) and the transcription factor Foxp3." (PMID 34681881, 2021). "In the field of tumor immunology, the CD4+CD25+ regulatory T cell expressing transcription factor Foxp3+ has been described to highly inhibit anti-tumor immunity." (PMID 33987190, 2021). "For four of the five patients for whom post-vaccination tumor samples were obtained, the CD8/FoxP3 ratio increased." (PMID 34885150, 2021). "We found that the number of apoptotic tumor cells increased along with the increased number of CD8+ T cells within the tumors, whereas the number of CD4+ T cells and FoxP3+ regulatory T cells (Tregs) decreased with topical IMQ." (PMID 34439104, 2021). "For example, CD4+ FOXP3+, CD4+, Th2 cells, macrophages, and MDSC cells promote growth by activating synergistic pathways between the immune microenvironment and tumor cells." (PMID 34205709, 2021). "We included tumor tissue samples and clinical data from 89 HCC patients in this study and performed immunohistochemistry for CD3, CD8, FoxP3, and CD31." (PMID 35049245, 2021). "There was a strong positive correlation between the infiltration of CD20+ B lymphocytes and other immune profiles (i.e., CD4+, CD8+, and FOXP3+ TILs, and CD68+ and CD163+ macrophages) both in stroma and tumor nests." (PMID 33494389, 2021). "In human cancers, human CD25 is mainly expressed on CD4+FoxP3+ Treg cells and in all tumor types studied, the level of CD25 expression in CD4+FoxP3+ Treg cells is also significantly higher than that in CD4+FoxP3− and CD8+ T cells." (PMID 34824364, 2021). "The median densities of CD3+, CD8+, FoxP3+ and CD20+ cells in the tumor compartment were 376.6 cells/mm2 (range 28.1 – 3497.6), 140.0 cells/mm2 (range 1.1 – 2511.9), 71.0 cells/mm2 (range 2.5 – 539.8) and 8.3 cells/mm2 (range 0 – 1494.8), respectively." (PMID 35046958, 2021). "With respect to FOXP3 expression, we observed an increased methylation in the gene body, after the promotor region, and increased RNA levels in CD4+ T cells from tumor." (PMID 34012510, 2021).
tumor (continued). "Several studies have shown that when tumor cells undergo EMT, Foxp3 reprograms T cell metabolism by suppressing glycolysis, enhancing OXPHOS, and increasing nicotinamide adenine dinucleotide (NAD) oxidation." (PMID 34576042, 2021). "High infiltration of tumor-infiltrating CD8+, CD4+, and FOXp3+ regulatory (Tregs) T cells and low CD163+ M2 macrophages (TAMs) were found to be significantly correlated with a longer overall survival in eCCA patients." (PMID 34083572, 2021). "A similar study of 196 NSCLC patients found improved overall survival for patients with increased tumor-infiltrating CD8+ T-cells, but poorer overall survival for patients with increased tumor-infiltrating FoxP3+ Tregs." (PMID 34141625, 2021). "We constructed a stably transfected PC cell line PANC‐1 expressing oe‐LINC00261, sh‐LINC00261, oe‐FOXP3, sh‐SCP2 or Vector and subcutaneously injected into a tumour model in mice." (PMID 34541823, 2021). "Since the role of T cells cannot be ignored in tumor growth and progression, we also analyzed CD4+ T cells, CD8+ cytotoxic T cells and CD4+CD25+Foxp3+ Treg cells in tumor-bearing mice." (PMID 34512367, 2021). "As opposed to CD103+CD8+ T cells, our in vivo studies showed a strong decrease in the frequency of CD103+FoxP3+CD4+ Treg in αV-knockout tumours, suggesting that CD103 expression in FoxP3+CD4+ and CD8+ T cells is regulated by distinct mechanisms." (PMID 34471106, 2021). "Previously, we showed the importance of reducing Tregs in the duodenum in NoV protective immunity, though simvastatin has been shown to increase FoxP3 expression in murine CD4 T cells in vitro and in tumor cells in mice." (PMID 34357979, 2021). "Evidence from past studies indicated that CDK4 depletion reduced infiltration of CD4+FoxP3+ Tregs, and CDK4 inhibitors increased tumor immunogenicity and cytotoxic T cell–mediated clearance of tumor cells." (PMID 34309585, 2021). "Aerobic exercise is able to increase the effective perfusion of tumor cells, and leads to a faster degradation of HIF‐1α and inhibits FoxP3+Treg recruitment." (PMID 34387383, 2021). "In a separate patient cohort (n = 11), T cells were classified using CD3, CD4, CD8, FoxP3, and granzyme B in paired PBMC and single cell suspensions of tumor samples." (PMID 34926643, 2021). "In contrast, Tregs, which are known as major immunosuppressive cells in the tumor microenvironment, seem to limit TA-HEV development in tumors as revealed by the induction of MECA-79+ TA-HEVs following depletion of Foxp3-expressing cells in Foxp3DTR mice." (PMID 33956259, 2021). "As shown in the results of the current cohort, some subtypes of TILs present in the residual tumor such as CD3, CD8, and CD4, as well as CD4/FOXP3 and CD8/FOXP3 ratios, influenced survival outcomes." (PMID 34858800, 2021). "Taken together, these findings indicate that a complex FoxP3-miR-150-IGF1R/IRS1-PI3K/AKT/mTOR feedback loop regulates OC pathogenesis, providing a novel mechanism for miR-150 as a tumor suppressor miRNA in OC." (PMID 33723215, 2021). "Analysis of T-cell spatial distribution revealed poor CD4+ and CD8+ cell infiltration within tumoural areas, where enrichment of CD4+/FOXP3+ was more prevalent." (PMID 33946676, 2021). "It has been suggested that tumor-infiltrating pDCs induce the activation and expansion of ICOS + Foxp3 + Treg cells to achieve immune suppression." (PMID 33790881, 2021). "Relative concentrations of IL6 and TGFβ in tumor tissues balance the differentiation of coexisting CD4+ RORγt+ Th-17 cells and regulatory CD4+ FoxP3+ RORγt+ IL17-negative T cells." (PMID 34804993, 2021). "After normalization of mRNA expression values of TGFβ1 and FoxP3 of HCC tumors to the values of matched peritumor tissues, we found an inverse correlation between the net tumor expression of these markers." (PMID 34769191, 2021).